IL1B (interleukin 1 beta)
Diseases named in the same sentence as IL1B in open-access papers (continued):
Sharing a sentence is not in itself a finding about the gene and the disease.
Sepsis (continued). "We have reported that inhibition of SphK1 improved the survival and lung vascular leakage in mice with cecal ligation and puncture (CLP)-induced sepsis by impeding NLRP3 inflammasome activation and subsequent IL-1β release from macrophages." (PMID 36798132, 2023). "In this study, a total of 33 putative targets were obtained by merging the SIN-targets and sepsis-related targets, and there were 3 genes with a higher degree: TNF-α, IL-6, and IL-1β." (PMID 37388447, 2023). "It was further found that prevention of necroptosis activation either by IL-1β-siRNA or RIP1 antagonist could improve the neurodevelopment deficit caused by neonatal LPS injection, suggesting that necroptosis contributed to neuronal loss or injury following neonatal sepsis." (PMID 37834141, 2023). "In this study, the protein levels of NLRP3, Caspase 1 p20, and IL‐1β in the myocardium of mice from the NR1H3‐KO + CLP group were significantly higher than those from the WT + CLP group, suggesting that NR1H3 deficiency could lead to activation of NLRP3 signaling pathways during sepsis." (PMID 37206244, 2023). "In our previous study, in the sepsis model induced by the cecal ligation puncture, TCE significantly reduced TNF-α, IL-1β, IL-6, TOS, OSI levels, increased TAS values, and significantly decreased caspase-3 and NF κB expression." (PMID 37476882, 2023). "After inducing sepsis by cecal ligation and puncture (CLP), HDC-knockout mice exhibited reduced plasma histamine levels, and the increase in TNFα, IL‐1b, IL‐6 and MCP1 levels in sepsis were attenuated when there was a lack of plasma histamine." (PMID 36823620, 2023). "In sepsis-induced AKI, high IL-1β, IL-6, TNF-α, and cell fragments negatively affect renal tubular epithelial cells." (PMID 36632449, 2023). "IL-10 is an anti-inflammatory cytokine while IL-1β, INF-γ, and COX-2 are expressed during pathological inflammatory conditions, such as sepsis." (PMID 36662218, 2023). "In a rat model of sepsis-induced AKI, paeonol treatment showed protective effects by lowering serum levels of TNF-α and IL-1β and suppressing NF-κB signaling in renal tissue." (PMID 36744251, 2023). "The mRNA and protein levels of IL-1β and IL-6 were significantly decreased in lung and spleen tissues from ATB1021-treated mice with sepsis compared to vehicle-treated mice." (PMID 36720915, 2023). "In contrast, LPS increased the supernatant IL-1β, IL-6, IL-8, IL-10, and TNF-α concentrations at 24 and 48 h better in patients with trauma than sepsis." (PMID 36615909, 2023). "Prior research has demonstrated that sepsis can lead to the buildup of proinflammatory cytokines, such as tumor necrosis factor-alpha (TNF-α) and interleukin-1β (IL-1β), within the pulmonary system." (PMID 37970921, 2023). "Treatment with 6-gingerol suppressed systemic IL-1β release and prolonged survival in mice with CLP-induced sepsis." (PMID 36744251, 2023). "Numerous studies have also shown that excessive release of pro-inflammatory cytokines, such as IL-1β, IL-6 and TNF-α, triggers pathophysiological abnormalities in sepsis and plays an important role in septic lung injury." (PMID 36737780, 2023). "Consistently, the ELISAs of TNF-α, IL-1β and IL-6 showed that the serum TNF-α, IL-1β and IL-6 levels in the sepsis group were higher than those in the control group." (PMID 36544058, 2023). "During sepsis, pro-inflammatory cytokines such as TNF-α and IL-1β are released by sentinel innate immune cells at the infection site and activated by pathogen-associated molecular pattern (PAMPS) and damage-associated molecular pattern (DAMPS)." (PMID 37575989, 2023). "NM administration significantly diminished the plasma levels of IL-1β, TNF-α, and IL-6 compared to the sepsis control." (PMID 35345558, 2022). "Previous reports have shown that the M2 isoform of pyruvate kinase muscle 2 (PKM2) regulates glycolysis to promote IL-1β and HMGB1 release in LPS-stimulated macrophages during sepsis pathogenesis." (PMID 34697412, 2022).
Sepsis (continued). "The 24-h proinflammatory cytokine levels were higher, and these data corroborate with previous results, which indicate increased concentrations of IL-1β and TNF-α early after sepsis, with a peak increase between 18 and 48 h after CLP induction." (PMID 36333747, 2022). "Patients in the sepsis group had higher PCT, WBC, CRP, IL-1β, IL-2, IL-6, IL-8, IL-10, IL-12, IL-17, IFN-γ, and SOFA scores than those in the infection group, and the difference was statistically significant (P < 0.05)." (PMID 35937269, 2022). "All three glial types responded with secretion of the pro-inflammatory cytokines IL-12, TNF-α, IL-1β, IL-17 and IFN-γ, which are also secreted at high levels in mouse models of S. agalactiae sepsis." (PMID 35281448, 2022). "The sepsis-induced activation of p38 MAPK was paralleled by a massive increase in the systemic levels of proinflammatory cytokines, such as TNF-α, IL-1β, IL-17 and IL-6, as well as the anti-inflammatory cytokine IL-10." (PMID 35178052, 2022). "Pharmacological inhibition of mitoNEET using mitoNEET ligand-1 (NL-1) decreased the levels of pro-inflammatory cytokines such as IL-1β, IL-6, and TNF-α in animal models of sepsis, as well as LPS-induced inflammatory responses by macrophages in vitro." (PMID 35136051, 2022). "The blood glucose level of patients with sepsis was positively correlated with the levels of IL-6, TNF-α, and IL-1β." (PMID 35664433, 2022). "MFA, especially at the highest dose, reduced cytokine levels (IL-1β, IL-18, and TNF-α) in the early stages of sepsis, favoring a balance of the immune system and of equilibrium of inflammatory components, crucial for the development of a favorable outcome." (PMID 36333747, 2022). "The study found that both the ACF and HJD can inhibit the release of inflammatory factors (NO, IL-1β, IL-6, and TNF-α), reduce inflammatory cell infiltration, and induce organ damage by sepsis." (PMID 36160407, 2022). "The blood glucose level of patients with sepsis was positively correlated with the levels of IL-6, TNF-α, and IL-1β and was negatively correlated with the levels of CD4+/CD8+." (PMID 35664433, 2022). "During the early stage of CLP-induced sepsis, the body activates inflammatory responses and secretes early pro-inflammatory mediators, such as TNF-α and IL-1β, to protect against infection." (PMID 35225146, 2022). "FTB, DNase1, FTB + DNase1, Cl-amidine, and FTB + Cl-amidine treatment lowered the levels of CRP, IL-6, IL-1β, and TNF-α in rats with sepsis." (PMID 36408247, 2022). "Sham-operated feces recipients showed a higher 5-day survival rate and a lower level of proinflammatory cytokines (IL-1β, P < 0.001; TNF-α, P = 0.001) than saline-treated feces recipients, indicating that sepsis-induced gut dysbiosis exacerbates sepsis." (PMID 35658593, 2022). "Clinical studies have found that in patients with severe sepsis, the blood levels of TNF-α, IL-1β, IL-6, IL-8, IFN-γ, and MCP-1 are significantly increased." (PMID 35370629, 2022). "In a mice model of lethal sepsis, quercetin significantly attenuated LPS-induced production of TNF-α and IL-1β in RAW264.7 macrophages, and also inhibited the LPS-stimulated phosphorylation of the inhibitors of κB kinase (IKKs), Akt, and JNK." (PMID 36588685, 2022). "In a cohort of 156 sepsis patients of whom 41 with ALI and 32 with ARDS, miR-155 levels are higher in patients with ALI or ARDS, positively correlate with IL-1β and TNF, and negatively correlate with PaO2/FiO2 ratio." (PMID 35990654, 2022). "In the case of the UPS cargos whose excessive release provokes pathologies, such as IL-1β in diabetes and AD, α-synuclein in PD, and HMGB1 in sepsis, downregulation of their releases would be beneficial for disease control." (PMID 35774225, 2022). "IL-1β is primarily released from the activated NLRP3 inflammasome, which plays a pivotal role in the pathogenesis of sepsis." (PMID 35178052, 2022).
Sepsis (continued). "Collectively, the findings of the present study demonstrated that HSF1 not only inhibited the development of ALI in sepsis but also suppressed the NLRP3 inflammasome activation and IL-1β maturation." (PMID 35720321, 2022). "proved that the activity of bone marrow-derived macrophages in sepsis mice was inhibited after treatment with HMGB1, leading to the increased release of IL-1β and IL-18 through caspase-11-dependent pyroptosis." (PMID 35572571, 2022). "Nicotine (17.5 ± 2 mg/kg, 7 ± 0.8 mg/kg, s.c.)pretreatment reduced the mortality during the early phase of sepsis and reduced the concentrations of TNF-α, IL-1β, IL-6, and MIP-2 after 2 or 10 h of sepsis." (PMID 35251010, 2022). "The serum levels of IL-1β, IL-6, TNF-α, and IFN-γ levels were increased in the acute phase of sepsis (one day after the surgery, CLP group) as compared with sham mice, suggesting an enhanced systemic inflammatory reaction." (PMID 36148090, 2022). "The current findings showed that FP-induced and PCP-pretreated sepsis mice resulted in lower TNF-α, IL-6, and IL-1β contents in plasma, downregulating expression of Treg cells in the spleen." (PMID 35694296, 2022). "mRNA expression levels of the NF-κB p65 subunit, IL-1β, and ICAM-1 were significantly increased in the aortas of mice with LPS-induced sepsis." (PMID 35328486, 2022). "ELISA showed that CLP-induced sepsis promoted the expression of inflammatory factors TNF-α, IL-1β, and IL-6." (PMID 35979014, 2022). "In summary, we used a cytokine cocktail comprising of TNF-α, IL-1β and IFN-γ to treat different organ-specific ECs for 4 h or 24 h and modelled the cytokine-induced changes as observed in sepsis." (PMID 35955534, 2022). "The expression of NLRP3, Caspase-1, GSDMD, IL-1β, and IL-18 was decreased, suggesting that ALDH2 also inhibited pyroptosis in sepsis-induced lung injury." (PMID 35188436, 2022). "Experimental sepsis led to a systemic cytokine storm resulting in the formation of excessive amounts of both pro-inflammatory cytokines (TNF-α, IL-1β, IL-17 and IL-6) and the anti-inflammatory cytokine IL-10." (PMID 35178052, 2022). "In this study, our results showed that the levels of IL-1β and IL-6 in the lung were increased by LPS treatment and this was significantly inhibited by terrein treatment, suggesting that terrein might be a therapeutic candidate for the treatment of acute lung injury induced by sepsis." (PMID 36422559, 2022). "lncRNA CRNDE was upregulated in patients with sepsis and SA-AKI models, and CRNDE overexpression markedly boosted inflammatory cytokine levels, including TNF-α, IL-6, IL-8, and IL-1β." (PMID 35464083, 2022). "However, it is controversial whether TH might trigger infectious complications through a pro-inflammatory effect (including sepsis) or by creating a “sepsis-like” syndrome via an increase in pro-inflammatory cytokines, including interleukin (IL)-1β, IL-8, and tumor necrosis factor (TNF)-α." (PMID 35268485, 2022). "The cytokines production leads to cascades of effects in the onset of sepsis, including pro-inflammatory factors such as TNF-α, IL-1β, and IL-6." (PMID 35510354, 2022). "Cytokine adsorbers have been used to treat sepsis or ALI by reducing the levels of cytokines such as IL-6, IL-1β and TNF-α11,18–20." (PMID 35882835, 2022). "Consistent with the fact that the upregulated production and release of cytokines and chemokines contribute to sepsis and organ dysfunction, such as TNF-α, IL-6, and IL-1β, are positively related to multiple organ dysfunction syndrome (MODS) and mortality." (PMID 35184141, 2022). "In sepsis, the inflammatory cytokines include tumor necrosis factor-α (TNF-α), interleukin-18 (IL-18), and interleukin-1β (IL-1β)." (PMID 36199375, 2022). "Sepsis is shown to impair CREB in lung endothelial cells, partly due to IL-1β-induced vascular leakage." (PMID 35892657, 2022). "Sepsis-exos increased the level of miR-885-5p, decreased HMBOX1, elevated IL-1β and IL-18, and promoted pyroptosis in AC16 cells." (PMID 35345489, 2022).
Sepsis (continued). "In the in vitro and in vivo model of sepsis, the up and down molecules of the IL-17 signaling pathway (HMGB1, RAGE, IL-17A, NK-κB) and inflammatory factors (IL-1β, IL-18) were upregulated." (PMID 36406124, 2022). "The correlation matrices in the sepsis group produced a single cluster showing a positive interaction among the pro-inflammatory mediators (CCL3, CCL4, IL1β, IL-6 and TNFα)." (PMID 35811678, 2022). "IL-1β, TNF-α, IL-10 and IL-6 are pro-inflammatory cytokines that play core roles in the pathogenesis of sepsis." (PMID 35225146, 2022). "Since IL‐1β is known to be elevated during sepsis, we tested the ability of P2X7R antagonist AZ106 to prevent vascular dysfunction in response to IL‐1β as proof of concept." (PMID 35668576, 2022). "In another study, high concentrations of IL-1β and TNF-α and a large number of cells labeled with IBA-1 were found in the early stages of sepsis in an animal model of sepsis induced by the CLP surgery." (PMID 36333747, 2022). "Taken together, CD40L–CD40 signaling pathway participates in the activation of EGCs during sepsis and affects the release of inflammatory factors TNF-α and IL-1β of EGCs, thereby affecting the intestinal barrier permeability." (PMID 36303116, 2022). "Sepsis induced an overexpression of the inflammatory mediators TNF-α, (p < 0.001) IL-6, (p < 0.001), IL-1β (p < 0.001) and IL-10 (p < 0.01)." (PMID 35795581, 2022). "Mice with LPS-induced-sepsis who were treated with BPF had lower serum levels of IL-6, TNF-α, IL-1β, CXCL1, and CXCL2 than the control mice treated with BPF." (PMID 36361915, 2022). "At the same time, the use of resveratrol in the CLP sepsis rat model decreased the sepsis-induced cardiomyocyte apoptosis and reduced the inflammatory cytokine TNF-α in serum and IL-1β in myocardial tissues." (PMID 35222035, 2022). "We found that fisetin induced mitophagy, which promoted clearance of sepsis‐mediated damaged mitochondria and scavenging of ROS, furthermore, blocked NLRP3 inflammasome activation of CMECs and inhibited the release of IL‐1β into CNS." (PMID 34837343, 2022). "Sepsis induced a significant increase in the mRNA levels of the inflammatory marker IL-6 (p < 0.05) whereas the gene expression of TNF-α and IL-1β was reduced (p < 0.01 and p < 0.05, respectively)." (PMID 35795581, 2022). "Previous studies have demonstrated that NETs can induce macrophage pyroptosis, elevate caspase-1 with increasing NETs dose, and increase inflammatory cytokines IL-1β and TNF-α in sepsis." (PMID 36430491, 2022). "Simultaneously, inflammatory cytokines such as IL-1β and IL-6 activate microglia through the damaged BBB, leading to brain cell destruction and even apoptosis during sepsis." (PMID 35958583, 2022). "Furthermore, the overexpression of miR-22 can reduce the expression of inflammatory factors (IL-1β, IL-6, and TNF-α) and NO, as well as significantly reduce cell apoptosis via PTEN/high-mobility group Box 1 (HMGB1) and TLR4/NF-κB pathway, thereby alleviating the AKI caused by sepsis." (PMID 35464083, 2022). "Meanwhile, we have also analyzed IL-1β and TNF-α expressions in serum, both of which are pro-inflammatory factors and play a vital role in promoting sepsis." (PMID 35252164, 2022). "BAFF significantly promotes the secretion of serum IL-1β, TNF-α, IL-6 and other inflammatory factors in the LPS-induced sepsis model whereas neutralization of BAFF markedly inhibits pro-inflammatory factor release." (PMID 35320937, 2022). "Regarding transcripts regulation, landiolol up-regulated the transcript of IL-1b in OVR females and potentiated the sepsis-induced increase of TNFα." (PMID 35322092, 2022). "Similar results have been reported in other models; in an in vitro sepsis model, co-stimulation of ITZ and lipopolysaccharides (LPS) increased gene expression levels of IL-1β." (PMID 36145686, 2022).
Sepsis (continued). "In a classic Sprague‒Dawley rat model of sepsis peritonitis, resveratrol significantly decreases LPS-induced expression of NF-κB, TNF-α, IL6, IL-1β, and TLR4 and increases the expression of p-PI3K, p-AKT, and p-mTOR in the myocardium." (PMID 36483739, 2022). "In CLP mice, there was a positive correlation between the MSS and the level of serum IL-1β, indicating that the MSS reflected the severity of sepsis induced by CLP in these mice." (PMID 36016572, 2022). "A large number of pro-inflammatory factors, such as TNF-α, IL-1β, and IL-6, and endotoxins can act on the BBB and then increase permeability in the process of sepsis." (PMID 36552192, 2022). "Compared with those in the sham group, the levels of IL-6, IL-1β and TNF-α in the sepsis group were increased (P < 0.05), the MDA content was increased, and the SOD and CAT activities were decreased (P < 0.05)." (PMID 35576220, 2022). "In parallel, for the sepsis parameters, serum TNF-α, IL-1β, IL-6, IL-8, endotoxemia, and blood-bacteria-free DNA in severe cases were higher than other groups and most of the levels of these parameters were different between COVID-19 severities." (PMID 35406667, 2022). "CLP-induced sepsis can produce inflammatory mediators including IL-6, TNF-α, and IL-1β, which aggravate inflammation." (PMID 35979014, 2022). "Epinephrine is able to inhibit LPS-induced responses by decreasing IL-1β, IL-8, and MCP-1 production, relevant during sepsis." (PMID 36425123, 2022). "In the initial stage of sepsis, increased inflammatory cytokines (TNF-α, IL-6, and IL-1β) lead to an inflammatory cytokine storm, which is a main cause of death in this stage." (PMID 35706715, 2022). "In the current study, activation of the NLRP3 inflammasome accompanied by increased secretion of IL-1β, IL-18, and HMGB1 was noted in CD11c+CD11bintMHC-IIhiCD115−Flt3+ splenic DCs after induction of sepsis." (PMID 34741186, 2021). "As compared to the values of the saline-treated sepsis groups, all the treatments resulted in significantly lower CitH3 and MPO values, whereas IL-1β was lower only in response to SZR-104 treatment." (PMID 34475875, 2021). "The cytokines IL-1β, IL-6, and TNF-α mediate the immunopathological features of sepsis and are released by neutrophils to exacerbate acute inflammation." (PMID 33588861, 2021). "For example, lncRNA PVT1 induces an increase in TNF-α, IL-6, and IL-1β release, and promotes inflammation by regulating TNF-α and JNK/NF-κB signaling pathways in sepsis." (PMID 33710444, 2021). "In vitro experiments showed that IL‐1β via its receptor contributes to transcriptional regulation of selected ALP genes, suggesting that it is involved in sepsis‐induced cardiac atrophy." (PMID 34472725, 2021). "For example, in cecal-ligation and puncture (CLP)-induced sepsis mice, deletion of TLR4 or TLR2 resulted in significantly decreased levels of pro-inflammatory cytokines (i.e., IL-1β, TNF-α, IL-6, and IL-8) and preserved tissue damages." (PMID 34884813, 2021). "Previous studies showed that TNF-α and IL-1β produced by macrophages activated neutrophils during sepsis, and high concentrations of TNF-α and IL-1β have been reported in BALF from ARDS patients." (PMID 34641966, 2021). "It is therefore plausible that KYNA and its derivatives inhibit NET formation during sepsis through the inhibition of TNF-α and HMGB1 release and IL-1β activation." (PMID 34475875, 2021). "In sepsis, lipopolysaccharide (LPS) and inflammatory cytokines, such as TNF-α, IL-1β, IL-6, and IL-17, can regulate the level of G-CSF." (PMID 34795984, 2021). "The activation of NF-κB participates in the occurrence and development of sepsis by enhancing the transcription of various proinflammatory cytokines, including TNF-α, IL-6, and IL-1β." (PMID 34721636, 2021). "The sepsis-induced increases in MPO and CitH3 levels in plasma were significantly reduced by KYNA and its analogues, and IL-1β plasma levels were also positively influenced by SZR-104." (PMID 34475875, 2021).